TREML1 (triggering receptor expressed on myeloid cells like 1)
Description:
Cell surface receptor that may play a role in the innate and adaptive immune response.
Synonyms: TLT-1; TLT1; dJ238O23.3; GLTL1825; PRO3438
Tractability: Small molecule: it has a binding pocket of medium quality. Antibody: UniProt places it where antibodies can reach, with high confidence; its Gene Ontology location is reachable by antibodies, with high confidence; UniProt predicts a signal peptide or a membrane-spanning region.
Gene: Protein-coding gene on chromosome 6 (41,149,167 to 41,155,553, reverse strand). Ensembl gene ENSG00000161911.
Subcellular location: Cell membrane; Cytoplasm
Subcellular location (Human Protein Atlas): Cytosol; Nuclear speckles; Golgi apparatus; Plasma membrane
Pathways (Reactome):
Immune System: Immunoregulatory interactions between a Lymphoid and a non-Lymphoid cell
Gene Ontology:
Molecular function: protein binding; transmembrane signaling receptor activity
Biological process: innate immune response; platelet activation; signal transduction
Cellular component: cytoplasm; cytosol; plasma membrane; membrane; cell surface; platelet alpha granule
Genetic constraint (gnomAD): Loss-of-function variants: 27 observed, 25.65 expected, observed/expected ratio (o/e) 1.05, 90% interval 0.77 to 1.45. The upper end of that interval is the gene's LOEUF score, 1.45, which puts it in group 6 of 6, group 1 being the genes least tolerant of losing a copy. Missense variants: 356 observed, 403.44 expected, observed/expected ratio (o/e) 0.88, 90% interval 0.81 to 0.96. Synonymous variants: 153 observed, 170.7 expected, observed/expected ratio (o/e) 0.9, 90% interval 0.79 to 1.02.
Homologues: Orthologues: chimpanzee TREML1 (99% identical), macaque TREML1 (96% identical), dog TREM2 (71% identical), pig TREML1 (71% identical), mouse Treml1 (68% identical), rat Treml1 (67% identical), guinea pig TREML1 (59% identical). Paralogues in human: PIGR (20% identical), CD300LG (16% identical), FCMR (16% identical), CD300LF (15% identical), CD300E (15% identical), CD300LB (15% identical), CD300A (15% identical), CD300C (15% identical), FCAMR (14% identical), TREM2 (14% identical), CD300H (13% identical), CD300LD (13% identical), and 1 more.
Diseases named in the same sentence as TREML1 in open-access papers:
TREML1 is named in the same sentence as 20 diseases in open-access papers, as found by Europe PMC text mining. Sharing a sentence is not in itself a finding about the gene and the disease. The quoted sentences say what the papers report.
Sepsis (4 papers, 2016 to 2022). Sepsis is defined as life-threatening organ dysfunction caused by a dysregulated host response to infection. "The MYL9-centered hub shares entities TREML1 with adult healthy controls and TGFB1l1 with adult sepsis." (PMID 32318053, 2020). "TLT-1 knockout mice (treml-1-/-) had increased gene and protein expression of inflammatory cytokines in the lungs and plasma after CLP induces sepsis." (PMID 35784361, 2022). "CMTM5, SELP, and TREML1 were also observed in pediatric resolved SIRS, in addition to ALOX12 (arachidonate 12-lipoxygenase, 12S type), which was also seen in pediatric sepsis." (PMID 32318053, 2020). "It interacts with TREML1, CMTM5, TGFB1l1, and ITGA2B in adult SIRS, among others and TGFB1l1 only in adult sepsis." (PMID 32318053, 2020). "Gene entities shared between sepsis and severe sepsis response hubs are; TDRD9 – LIN7A, GPR84 – ENTPD7, PYCT1A and ZDHHC19, CD177 – DDAH2 and RGL4, SLC16A3 – DENND3 and MBD6, MYL9 – CMTM5, ITGB3, ITGA2B, NRGN, SELP and TREML1." (PMID 32318053, 2020).
Alzheimer disease (2 papers, 2019 to 2025). A progressive, neurodegenerative disease characterized by loss of function and death of nerve cells in several areas of the brain leading to loss of cognitive function such as memory and language. "TREML-1 is widely expressed in microglia and its levels in the brain have been associated with decreased risk of developing Alzheimer disease in humans." (PMID 40948752, 2025). "Particularly, TREML-1 can enhance the calcium signalling in an SHP2 (PTPN11)-dependent manner, whereas some genetic variant of TREML-2 have been identified to be protective for Alzheimer’s disease, contrary to TREM-2 genetic variants." (PMID 40948752, 2025). "Background: rs9357347 located at the triggering receptor expressed on myeloid cells (TREM) gene cluster could increase TREM2 and TREM-like transcript 1 (TREML1) brain gene expression, which is considered to play a protective role against Alzheimer’s disease (AD)." (PMID 31379492, 2019). "Moreover, finding new molecules that can act via TREML-1 could modulate the activity of TREM-2, and vice-versa On the other hand, also targeting TREML-2 could open to new strategies for the treatment of Alzheimer’s disease, highly enhancing the rate of success." (PMID 40948752, 2025).
amyloid (1 paper, 2018). "Whether exaggerated Treml1, which is observed in the Velocigene Trem2−/− mice, is also playing a protective role when crossed to an amyloid model of disease is unknown." (PMID 29040522, 2018).
autoimmune disease (1 paper, 2023). A disorder resulting from loss of function or tissue destruction of an organ or multiple organs, arising from humoral or cellular immune responses of the individual to their own tissue constituents. "TREML1, CAPN1, and DBN1 seem the most relevant based on their functions in immune responses, cytoskeletal remodeling, cell adhesion/migration and association with chronic inflammatory and autoimmune diseases." (PMID 37205098, 2023).
lung adenocarcinoma (1 paper, 2021). A carcinoma that arises from the lung and is characterized by the presence of malignant glandular epithelial cells. "However, there is no research on TREML1-associated lung adenocarcinoma." (PMID 33619234, 2021).
polycystic ovary syndrome (1 paper, 2023). A disorder that manifests as multiple cysts on the ovaries. "We constructed a logistic model using these protein markers, where HIST1H4A (OR=1.037) was an independent risk factor for polycystic ovary syndrome and TREML1 (OR=0.976) were protective factors for the disease." (PMID 37854181, 2023).
prostate carcinoma (1 paper, 2021). A carcinoma that arises from epithelial cells of the prostate gland. "And some studies have shown that TREML1 is a prognostic gene of prostate cancer." (PMID 33619234, 2021).
tumor (3 papers, 2021 to 2023). "Recently, in a large-scale computational study on previous tumor datasets reporting markers of T cell exhaustion, TLT-1 (TREML1) was among the top upregulated markers associated with T cell dysfunction; however, its role in antitumor immunity has not yet been explored." (PMID 36305874, 2023). "Therefore, it is necessary to further experiment with the role of TREML1 in the tumor in future research." (PMID 33619234, 2021).
TREML1 also shares sentences with these, for which no sentence is quoted: COVID-19 (2 papers); atherosclerosis (1); bacterial infection (1); cancer (1); carotid artery thrombosis (1); coronary artery disease (1); dementia (1); Insulin resistance (1); lung carcinoma (1); Obesity (1); pulmonary embolism (1); thrombosis (1).